IL15 (interleukin 15)
Diseases named in the same sentence as IL15 in open-access papers (continued):
Sharing a sentence is not in itself a finding about the gene and the disease.
infection (continued). "Indeed, WT E. ictaluri induces transcriptional upregulation of IL-8 and IL-15 compared to a ΔEseN mutant, which would result in an enhanced inflammatory response, the recruitment of phagocytes, and phagocytic activation at the site of infection." (PMID 35889053, 2022). "Given that NK cells participate in antiviral responses, and that IL-15 is a cytokine with an important role in the proliferation and biology of NK cells, it is of interest to determine the role of these cells as inflammatory drivers or infection-resolving agents." (PMID 36700209, 2022). "Similarly, we also analyzed and found the gene expression of IL-15 was markedly increased in GBM cells after infection with Ad5-Ki67/IL-15 using RT-PCR (more than 200-fold compared to the control group), while lower IL-15 levels were maintained in untreated GBM cells." (PMID 33133514, 2020). "In contrast to activation-induced cytokines, expression of the anti-apoptotic cytokine IL-15, implicated in the development and maturation of memory CD8+ T cells, was restricted to MAIT cells in their resting states: human unstimulated MAIT cells or murine MAIT cells at the resolution of infection." (PMID 31533045, 2019). "We therefore hypothesized that the inhibition of IL-15, in combination with antibiotics, might represent a useful therapy that would reduce inflammation and joint destruction but preserve the host's ability to clear the infection." (PMID 29440371, 2018). "It is possible therefore that, in vivo, IL-12 may contribute to NK cell IFN-γ production when γc cytokines are lacking, such as during primary exposure (when IL-2 from antigen-specific T cells may be limiting) or later in infection when IL-15 signaling is reduced by changes in receptor expression." (PMID 27047490, 2016). "mRNA expression of CD122 as determined from microarray data and surface expression of CD122 as detected by flow cytometry, increased with time in CD62Lhi memory P14 cells, suggesting that sensitivity to IL-15 could increase in CD62Lhi memory CD8 T cells with time after infection." (PMID 26485703, 2015). "However, other qualitative aspects of memory CD8 T cells including proliferation in response to the homeostatic cytokine IL-15 or to Ag, and mitochondrial function increased with time after infection when both the memory CD8 T cell population, and defined CD62Lhi subsets were analyzed." (PMID 26485703, 2015). "Additionally, in these mice infection induced serum IL-15 and TNF-α expression." (PMID 23405155, 2013). "At 24 h after infection with L. infantum, we observed a 2- to 2.5-fold increase of the percentage of IL-15Rα+ mDC in the spleen, indicating that L. infantum might modulate the IL-15/IL-15R system." (PMID 20213736, 2010). "Dynamic infection-responsive genes, including CXCL10, CXCL11 and IL15, exhibited robust antiviral signatures, which highlighted Mac_CD163 as key cellular mediators in the immune response to ASF." (PMID 42216858, 2026). "For the cell host response in the early-phase infection, genes such as JUN, IL15, ATF2, TNFSF15, and CXCL10 were significantly upregulated, reflecting a strong pro-inflammatory and immune response." (PMID 40649996, 2025). "Four weeks post infection with M.tb HN878, we observed a significant increase in circulating IFN-γ, TNF-α, IL-1β, IL-2, IL-6, IL-12p70, IL-17A/F, IL-15, and IL-33 levels in mice immunized with ID93+EmT4TM compared to saline controls." (PMID 40285479, 2025). "Second, the IL-13-induced secondary inflammatory cluster–enriched for IL-15, TNF-NFκB signaling, ER stress, and cell-death pathways–was most strongly induced at later infection timepoints." (PMID 41427379, 2025).
infection (continued). "During early-phase infection, there was robust upregulation of pro-inflammatory cytokines such as JUN, IL15, ATF2, TNFSF15, and CXCL10, indicating strong immune activation." (PMID 40649996, 2025). "Animals that survived infection also had transiently increased levels of IL-1β, IFN-γ, IL-15, G-CSF, and IL-2, each of which returned to baseline at ≈10–14 d post-exposure, suggesting regulation of a systemic inflammatory response." (PMID 41460894, 2025). "Concerning cellular immune response, levels of mice serum cytokines; IFN-γ, IL-15 and TNF-α were significantly higher (P < 0.001) after 10 and 21 days of infection as compared to healthy mice." (PMID 40029925, 2025). "The levels of CXCL10/IP-10 and IL-15 in BAL fluid peaked in both the lean and obese groups during the acute phase of infection, with CXCL1-/IP-10 levels exhibiting the most dramatic increase." (PMID 40027795, 2025). "IL-15 generates and maintains long-term CD8+ T-cell immunity against Toxoplasma gondii and controls intracellular pathogen infection." (PMID 40431182, 2025). "We next tested the effects of IL-15 and IL-21 on EBV latency gene expression at day 10 post-infection." (PMID 38683861, 2024). "To evaluate the combination of an IAPi/SMACm ± IL-15 superagonist and SIV Env-targeting RhmAbs to reduce the established viral reservoir, we used a macaque model of SIVmac239 infection with ART-mediated suppression of viral replication." (PMID 37783968, 2023). "CAST/EiJ mice were protected from mortality by IL-15 therapy when CD8+ and CD4+ T cells were eliminated prior to infection with MPOX." (PMID 37533932, 2023). "The overarching pattern pertaining to the remainder tested including IL-15, eotaxin-1, GRO-α, MCP-1, and IL-1RA reflects a stepwise increase in serum concentration over time, from day 0 to day 7 post-infection." (PMID 38035334, 2023). "More importantly, both SARS-CoV-2 and pCoV-GD01 infection induced the production of cytokines such as IFN-gamma, IL-12p70, IL-13, IL-2, IL-5, TNF-alpha, IL-17A, IP-10, MCP-3, MIP-1beta, MIP-2, Exotaxin, IL-15/15R, IL-28, IL-3, G-CSF, IL-1alpha and ENA-78." (PMID 37330497, 2023). "We evaluated the systemic and tissue parasitism, the survival and the body mass rate, the release of inflammatory mediators (TNF, IL-6, IL-15, CCL2 and creatine kinase) and the tissue inflammation at day 30 post-infection." (PMID 37505639, 2023). "In analyzes of lung homogenates 3 days post infection, BALB/c mice had higher protein levels of IP-10, IL-1β, TNF-α, M-CSF, IL-4, IL-12, IL-15 and IL-17." (PMID 36810092, 2023). "As the infection of HBV in vitro (HepAD38 and HepG2) as well as in vivo resulted in reduced expression of IL-15 and IL-11, we further checked if the treatment of immune modulators can elevate the expression of both cytokines." (PMID 36742132, 2023). "IL15 or IL15/IL15Rα complex induces robust proliferation of NK cells, NK T cells, memory CD8+ T cells, etc., promoting immune response and anti-infection." (PMID 38066992, 2023). "To determine if NK cells from Hu-NSG-Tg(IL-15) mice produce functional anti-HIV-1 responses, we performed flow cytometry to phenotype NK cells 8 weeks post-infection." (PMID 36851579, 2023). "During peripheral infection in ganglia, the CXCL10/CXCR3 signaling pathway is indispensable for recruitment of HHV-specific CD8+ T cells and IL-15 plays an essential role in selectively activating these cells." (PMID 35337341, 2022). "We stimulated CD4+ T cells from three different donors with equimolar concentrations of IL-2 and IL-15 and analyzed the expression of CDK9 and cyclin T1 after 8 to 9 days of stimulation, a time when latent and productive infection with HIV-GKO was measured." (PMID 35499323, 2022). "In this study, we found that E. ictaluri EseN modulates the host immune response by increasing IL-8 and IL-15, and reducing IL-12a and IL-6 cytokines during HKDM infection." (PMID 35889053, 2022).
infection (continued). "First, we monitored total infection with R5/X4 HIV-GKO (csGFP+/mKO2+, csGFP+/mKO2−, and mKO2+/csGFP−) over 7 days, in primary CD4+ T cells stimulated with IL-2 or IL-15 at equimolar concentration." (PMID 35499323, 2022). "Furthermore, IL-15 signaling may be paramount in the humoral response to infection and vaccination." (PMID 36430566, 2022). "A more persistent effect on cardiac fibrosis and systolic function at 35 days post-infection required the combined expression of IL9 with IL3, IL4, IL13, and IL15." (PMID 35508525, 2022). "The differentially expressed cytokines such as IL6, IL10, IL11, IL15, TNFSF10, TNFRSF6B and TNFAIP6 were detected in the lung of goats after Pm infection in this study." (PMID 35739866, 2022). "In influenza virus and S. aureus infection, mice that lack NK cells (Ncr−/−, Il15−/−, or depleted using anti-NK1.1 antibodies) show a higher lung viral or bacterial burden at the peak of infection and a longer infection period." (PMID 35844626, 2022). "We observed that R5/X4 HIV-GKO total infection (productive and latent), as well as cell viability, were higher in CD4+ T cells stimulated with IL-15 compared to IL-2 stimulated." (PMID 35499323, 2022). "Increased cytokines and chemokines such as IL-6, GM-CSF, IL-1a, IL-15, CXCL9 and CXCL10 and complement system components such as C3 were also observed from 6 to 36 months after infection in patients with chronic disease compared to with retrieved controls." (PMID 36189282, 2022). "After infection diagnosis, PGE2 showed only positive correlations with pro-inflammatory cytokines such as TNFα, IL-2, IL-15." (PMID 33617528, 2021). "In addition to their role in bystander activation, signaling through IL-15 and IL-18 receptors was previously shown to modulate the expression of natural killer receptors (NKRs) on EM cells thereby triggering their innate-like cytotoxicity and affecting the outcome of the infection." (PMID 33617602, 2021). "Among serum molecules identified in non-neurological and neurological diseases in the acute phase of the infection, 12 (IL-1β, IL-6, TNF, IL-2, IL-7, IL-17A, IL-15, IFN-α, IL-5, IL-13, IL10, and GM-CSF) were shared by both networks." (PMID 33776990, 2021). "Increases in IL-15, IL-1β, IL-6, and TNF-α levels were slightly more delayed in the CSF, beginning closer to day 6 post-infection." (PMID 34001896, 2021). "Type I interferons (IFNs, e.g., IFN-α), among other factors, are also produced rapidly in response to infections such as HIV/SIV, and they can induce production of IL-15." (PMID 34578331, 2021). "It was interesting to note the upregulation of inflammatory cytokines IL-15 and TNFα in response to PBMC infection with SPPV." (PMID 34211465, 2021). "Expression of chemokines involved in immune cell recruitment to tissue sites of infection, CCL5, CXCL10, CXCL9, and IL-15, were significantly lower in lung tissues of HTNV-infected Ifnar1-/- animals compared to WT controls." (PMID 32330200, 2020). "Our data suggest that physiological IL-15 signalling can drive high SRC in TVM cells, and that this can be further increased with recent infection and increasing age." (PMID 32504069, 2020). "In contrast with inflammatory cytokines TGF-β, MIP-1α, and TNF-α, IL-15 is elevated in animals resistant to SIV-PAH (P = 0.01) and is inversely correlated with increased pulmonary pressures at 6 months post-infection (left panel, P = 0.0097)." (PMID 31882598, 2019). "Other markers that were upregulated during the early active infection phase included IFN-γ, IL1-RA, IL-6, IL-10, IL-15, and IL-18; all of which have been reported in cases of human disease." (PMID 31557262, 2019). "Compared to ZIKV/Cambodia, the experimental infection of hiNPCs with ZIKV/Brazil resulted in a diminished induction of ISGs and lower induction of several cytokines (IFN-α, IL-1α/β, IL-6, IL-8, and IL-15), consequently favoring virus replication." (PMID 31474994, 2019).
infection (continued). "Compared with SG400-EGFP, infection with SG400-E2F1 and SG400-E2F/IL-15 both inhibited MDA-MB-231 cell growth in a dose-dependent manner; SG400-E2F/IL-15 exhibited a stronger inhibitive effect than SG400-E2F1 (P=0.0000)." (PMID 31278126, 2019). "Concentration of IL-15 reached 3ng/ml at 96 h after infection of MDA-MB-231, while low expression levels of IL-15 remained in MRC-5 cells." (PMID 31278126, 2019). "The cDC1 subset provides the antigen for priming by cross-presentation in this context of infection, but also provide specific signals 2 (CD24) and 3 (IL-12 and IL-15)." (PMID 30108585, 2018). "Furthermore, IL-15 secreted by phagocytic monocytes during the innate response is a growth factor for γδ T cells, promotes cytotoxicity by NK cells, and stimulates their secretion of INFγ and TNFα, thereby linking innate and adaptive immunity during infection with M. tuberculosis." (PMID 29770360, 2018). "Beside IL-15 and IL-18, NK cell activation depends on IL-2 that is predominantly produced by activated CD4+ T cells during many infections." (PMID 30210499, 2018). "cDC1s promote S1PR expression on CTLs, a key chemokine receptor facilitating CTL LN egress, and express high levels of the T cell survival cytokine, IL-15, to support CTL viability at the site of infection." (PMID 30622538, 2018). "Interestingly, one study demonstrated that IL-15 enhancement of IL-12 secretion by a PMA-activated U937 monocytic cell line was associated with increased ability to kill intracellular Leishmania parasites, suggestive of a potential role for such mechanisms in protection against infection." (PMID 29491009, 2018). "At 4 months after infection (T2), the dogs immunized with either salivary protein presented higher levels of IFN-γ, IL-6, IL-18, GM-CSF, IL-7, IL-15, TNF, and CCL2 when compared to controls." (PMID 30519235, 2018). "At T1, 2 months post-infection, the LM17- and LJL143-immunized dogs presented higher levels of IFN-γ, IL-6, IL-18, CXCL10, GM-CSF, IL-7, IL-15, and CCL2 in comparison to controls." (PMID 30519235, 2018). "It rapidly initiates a cascade of events characterized by the production of the early pro-inflammatory cytokines, IL-15, and IFN-α, quickly followed by the more sustained TNF-α and monocyte chemoattractant protein (MCP)-1 during infection." (PMID 30568659, 2018). "Differential changes in the expression of CCL19, CCL20, IL-8, IL-15, and Trail/TNF (ligand) superfamily members TNFSF10 and TNFSF15 in DT40 cells were also observed at different time points after vvIBDV infection." (PMID 28086922, 2017). "Interleukin gene activation was limited to IL1A, IL1B, IL7, and IL15 at 6 h, followed by a downregulated expression of all genes, except IL7, at 16 h of infection." (PMID 28993767, 2017). "Wild-type infection also induced IL-6, CCL2 (MCP-1), and CXCL1 at day 2 postinfection and suppressed IL-15 production compared to levels in mock-infected animals." (PMID 29138302, 2017). "Rapid and more-sustained elevations in IL-1ra, MIP-1α, IL-5, IL-10 and IL-17 levels were followed by IL-1β, IL-2, IL-7, IL-9, IL-12, IL-15, IFN-α2, MIP-1β, FGF-2 and GM-CSF at over 2 months post-infection, and accompanied by the recovery of CD4+ cells." (PMID 27830756, 2016). "We have analyzed transduction efficiencies (multiplicity of infection (m.o.i.)= 1) following stimulation of naïve T cells for 48 h with magnetic anti-CD3/CD28 beads and IL-7, IL-15 and IL-21." (PMID 27435312, 2016). "The rapid induction of IL-6, MCP-1, IL-15 and MIP-1α in serum at day 1 after infection suggests an immediate activation of the macrophage/monocyte/dendritic cell innate immune system." (PMID 25946071, 2015). "In regards to the mucosal inflammatory reactions, proinflammatory cytokines IL-1beta, IL-6, IL-15, IL-12 and IL-18 were all significantly lower in the lungs of SARS-CoV-infected aged animals at either day 5 or 10 post infection." (PMID 24642138, 2014).
infection (continued). "The severe infection group had significantly lower levels of IFN-γ, IL-4, IL-10, IL-15, and IFN-α2 during the CP than during the AP." (PMID 24646014, 2014). "At both 17 and 48 hours after infection, 12 cytokines were elevated (G-CSF, M-CSF, IFN-γ, IL-1α, IL-1β, IL-12p70, IL-15, IL-17A, IP-10, MCP-1, MIG, and MIP-1α) in infected mice compared to placebo-inoculated mice." (PMID 23520553, 2013). "In this study, expression levels of IL-4, IL-10, IL-13 and TNF-α were significantly up-regulated while the expression levels of IL-1β,IL-18,IFN-γ, IL-2, IL-15, IL-17F, IFN-α, IFN-β, IL-3 and CSF-1 were markedly decreased in PBMCs at all stages of infection." (PMID 24358317, 2013). "A variety of cytokines and chemokines were induced by both HRV 14 and/or HRV 16 infection that include FGF-Basic, chemokines and cytokines like IL-6, IL-15, MCP-2, IP-10, MIP-1β, type I IFN-α, type III IFN-λ2 (IL-28A), and ENA-78." (PMID 23799120, 2013). "The decreased levels of IL-2, IL-15, IFNα, IFNβ and IFN-γ indicated that infection of REV-A suppressed Th1-type immune response." (PMID 24358317, 2013). "Following infection of PBMCs with HSV-1, IL-15 production and release was responsible for stimulating cytotoxicity against infected cells and reducing viral replication." (PMID 24312353, 2013). "In our study, we demonstrated that stimuli that mimic infection (LPS, SEB or PMA) or pro-inflammatory mediators, as TNF-α or IL-2 or IL-15, induce the cell surface expression of HMGB1 and its secretion at 48 h or 14 days after treatment, respectively." (PMID 21915243, 2011). "In fact, there was down-regulation of genes involved in innate immune response like IL2, IL15 and STAT1 at early stages (4 and 8 hpi) of infection." (PMID 21439068, 2011). "IL-15 transcript levels returned to baseline values by day 5 pi, whereas IFN-γ and IL-2 induction was sustained until day 5 of infection." (PMID 21912714, 2011). "In particular, the levels of IL-7 and IL-15 obtained after MVA and MVA-B infection were approximately 100 fold higher than after mock-infection without maturation cocktail." (PMID 21625608, 2011). "Therefore, we investigated whether various activation signals, such as proinflammatory stimuli (TNF-α or IL-2 or IL-15), or signals that mimic infection (LPS, SEB or PMA), influence the cell surface expression and active secretion of HMGB1 by human cord blood cells." (PMID 21915243, 2011). "Similarly, IL-15 and MIG exhibited increased production withGBS infection in the decidua and placenta, while Lactobacillus reduced their production compared to GBS alone." (PMID 40459557, 2025). "Likewise, cytokines and chemokines including CRP, IL-15, IL-6, IP-10, MCP-1, TARC, MIP-1α, and IL-12p40 were increased following infection with WE-CL13-GP181M-185W-492I." (PMID 41086811, 2025). "Interestingly, mitogen-activated MLN cells showed a steady increased IL-15 levels starting on week 4 of infection in NLRP3−/− mice, whereas spleen levels were higher only at the chronic stage of infection." (PMID 38842647, 2024). "In WT mice, rIFNε treatment increases Ifng transcript levels in the uterus during infection, however, rIFNε treatment does not induce these IFNγ responses in Il15-/- mice (p = 0.527)." (PMID 38263527, 2024). "On the other hand, the levels of IL-1RA, IL-10, IL-12p70, IL-15, and IL-23 were not significantly different between the cells infected with the two bacterial species throughout the infection periods." (PMID 39042701, 2024). "Treatment does not significantly affect pre-pro-like NK cell numbers in the uterus during infection and does not change Ifne expression, demonstrating that IL-15 is incapable of driving IFNε expression and acts downstream." (PMID 38263527, 2024). "After resolution of infection, resident memory T cells (TRM) form and disperse in the skin to provide protective immunity and are particularly dependent on epithelial-derived factors, such as IL-7 and IL-15, supplied by keratinocytes." (PMID 37946298, 2023).